INS (insulin)
Diseases named in the same sentence as INS in open-access papers (continued):
Sharing a sentence is not in itself a finding about the gene and the disease.
diabetes (continued). "For example, in patients with non-alcoholic fatty liver disease (NAFLD) and diabetes, hepatocyte-derived fibrinogen-related protein 1 (HFREP1) induces IR by activating the ERK1/2 signaling pathway, inducing hepatocyte proliferation and disrupting insulin signaling in peripheral tissues (Wu H.-T." (PMID 40417223, 2025). "There are two possible etiologies of diabetes: a lack of insulin or insulin insufficiency." (PMID 40937409, 2025). "Diabetes is also related to immune function, and it is believed that the JAK/STAT/SOCS signaling pathway may significantly impact the development of diabetes due to its influence on insulin signaling and inflammation." (PMID 39968090, 2025). "Faecalibacterium is often reduced in individuals with metabolic disorders, including obesity, insulin resistance, and type 2 diabetes mellitus, and several studies have reported negative correlations between Faecalibacterium abundance and fasting glucose and/or insulin levels." (PMID 40732909, 2025). "Type of diabetes treatment (B = -0.108, β = -0.083, P = 0.049): This negative coefficient implies that participants on insulin or combination therapy might engage in slightly fewer self-care activities compared to those on oral medications only." (PMID 40666264, 2025). "Though deletion of Atg7 was not sufficient to induce diabetes,it could induce glucose intolerance,impaired insulin secretion especially when fed a high fat diet in mouse." (PMID 39996055, 2025). "Significant differences (p < 0.05) were identified among the three groups in terms of age, the duration of diabetes, HbA1c, C-peptide, GA, TG, HDL-C, eGFR, UACR, SAF, SUA, hypertension history, current smoking condition, the use of antihypertensive medications, and insulin injection." (PMID 40299327, 2025). "While diabetes‐specific screening for disordered eating behaviour is recommended, the only diabetes‐specific instrument available, Diabetes Eating Problem Survey‐Revised (DEPS‐R), focuses on type 1 diabetes and rapid‐acting insulin, limiting its use across diabetes types and treatment regimens." (PMID 40440439, 2025). "People with diabetes, whether or not they use insulin, must assume responsibility for the daily management of their disease." (PMID 40732150, 2025). "Thirdly, distinguishing insulin resistance in individuals with and without diabetes is crucial, as the latter may compensate with increased insulin secretion, which is not possible in those with diabetes." (PMID 40065358, 2025). "Women in the “insulin only” group had a higher risk of all-cause mortality (HR 1.18 (CI 1.11–1.25)) than women without diabetes, while in the “non-insulin GLD only” and “insulin and non-insulin GLD” subgroups, both women and men with diabetes had lower mortality risks than those without diabetes." (PMID 41350985, 2025). "Thirty-one patients with early postoperative SSI were enrolled in cases group, and the controls were matched (1:2) using the following criteria: gender (female/male), age (±3 y), diabetes (insulin/oral/no), date of surgery (morning/afternoon) and season of surgery (spring/summer/autumn/winter)." (PMID 41363553, 2025). "Additionally, the duration of diabetes, being on insulin or not, and the duration of insulin therapy were not significantly different between both groups." (PMID 39958094, 2025). "Whether or not a patient had diabetes or was taking insulin did not have a statistically significant impact on the length of hospital stay." (PMID 39764343, 2025). "Thus the search for a genetic defect in KATP (KCNJ11, ABCC8) or INS genes was justified, but the severe, non syndromic diabetes initially observed in our proband was not compatible with a loss-of-function GCK variant." (PMID 40244428, 2025). "This synergistic effect means that CGM could augment the glycaemic benefits of anti‐diabetes medications in people with T2D not using insulin." (PMID 40851538, 2025).
diabetes (continued). "Third, insulin users are highly likely to receive diabetes training, whereas OAD users do not." (PMID 40445527, 2025). "Moreover, participants who were not on diabetes medications had significantly higher odds of better HL levels compared to those on both oral medications and insulin (OR = 11.196 [95% CI, 1.138–110.201]; P = 0.038)." (PMID 41480240, 2025). "However, when comparing pregnant women with GDM to pregnant women without diabetes mellitus but with risk factors for hyperglycaemia, GDM was associated with reduced insulin secretion." (PMID 40691142, 2025). "A lack of insulin or insulin insufficiency destroys this important process and may lead to diabetes." (PMID 40937409, 2025). "Moreover, prior studies have primarily focused on specific groups, such as insulin or oral medication users, rather than addressing diabetes more broadly." (PMID 41049880, 2025). "Outcomes could be affected by diabetes duration and insulin usage duration among others; however, these data were not reliably documented in the E nor readily extractable automatically." (PMID 40804810, 2025). "It was found that those who were on treatment with both OHA and insulin had increased odds of being diagnosed with diabetes distress compared to those who were on OHA alone, with around 50% of individuals on both OHA and insulin suffering from diabetes distress." (PMID 41523497, 2025). "Insulin plays a key role in managing blood sugar levels, and without proper control, diabetes can result in high blood sugar (hyperglycemia), which may harm various organs, especially the nerves and blood vessels." (PMID 41280964, 2025). "Diabetes mellitus was recorded without stratification by glycemic control parameters, disease duration, or the presence of neurovascular complications and partially by treatment regimen (insulin-dependent or not)." (PMID 41301135, 2025). "Insulin has been described as an antigen in diabetes and non-diabetic conditions." (PMID 40821816, 2025). "In addition, there have been several developments in the pharmacology of non-insulin diabetes medicines, working on different aspects of gut and renal glucose absorption, hepatic metabolism, insulin sensitivity, and incretin hormone physiology." (PMID 40651878, 2025). "Additionally, a meta-analysis in adults without diabetes showed a relationship between moderate alcohol intake and reduced HbA1c and fasting insulin among all participants, but lower insulin sensitivity in women only." (PMID 41228532, 2025). "Also, the impact that GADD45A has on glucose uptake and insulin sensitivity point to that targeting GADD45A might be therapeutically useful to counteract some of the effects contributing to obesity and diabetes." (PMID 40301189, 2025). "Web-based questionnaires were distributed to representatives of all 121 pediatric diabetes centers participating in the SWEET initiative from March 1 to May 31, 2024, and used to map accessibility of and reimbursement for CGM, CSII, glucometers, and insulin." (PMID 40864470, 2025). "This insight is particularly relevant in the broader context of beta-cell replacement and diabetes management, where therapeutic strategies often focus on preserving or enhancing residual insulin secretion without always accounting for the impact of insulin sensitivity on metabolic outcomes." (PMID 40755872, 2025). "Historical data from 1984 also show a marked increase in diabetes prevalence among patients with CRC, supporting the hyperinsulinemia hypothesis, which posits that high serum insulin levels may promote colon tumor growth and act as a mitogen, thereby increasing CRC risk." (PMID 41372957, 2025). "The mechanism of PC-induced diabetes (pancreatogenic type 3c) has not been fully elucidated but is thought to be a paraneoplastic phenomenon, related to PC cell secretion of extracellular vesicles that mediate insulin resistance and B-cell dysfunction." (PMID 40439123, 2025).
diabetes (continued). "Moreover, our findings indicate that young people’s interactions with traditional health care systems, such as insulin prescriptions, diabetes reviews, and appointments, are not always positive experiences." (PMID 41115270, 2025). "We speculate that this was likely due to poorly controlled diabetes as they were not receiving insulin therapy." (PMID 40575255, 2025). "Since the participants with abnormal FBG were not diagnosed with diabetes in this study, in addition to the depressed symptoms mentioned earlier, insulin resistance may be our initial suspected contributing factor to TD." (PMID 40225726, 2025). "Additionally, these individuals had a higher incidenceof chronic obstructive pulmonary disease (COPD), acute myocardial infarction(AMI), and diabetes mellitus (DM), with greater usage of insulin and diureticsupon discharge, compared to those without MACEs." (PMID 41209141, 2025). "Glycemic control following pancreatectomy presents challenges, especially in patients with diabetes due to a lack of endogenous insulin, however, optimal management remains unclear." (PMID 40400655, 2025). "While one could argue that these culture conditions mimic the diabetic state, diabetes coincides with insulin resistance or lack of insulin production, which would typically limit the uptake of glucose by most cells despite the elevated concentrations." (PMID 40586776, 2025). "Diabetes is usually split into two types: Type 1 diabetes, an autoimmune disorder where the pancreas does not produce insulin or produces very little; and type 2 diabetes, which is more common and generally associated with lifestyle factors like obesity, poor diet, and lack of exercise." (PMID 41266649, 2025). "Cardiovascular and renal comorbidities of diabetes are increasing in LMICs and newer medications—specifically, sodium-glucose co-transporter-2 (SGLT-2) inhibitors and glucagon-like peptide-1 (GLP-1) receptor agonists—help mitigate these comorbidities more effectively than insulin alone." (PMID 40245017, 2025). "Moreover, advanced diabetes therapies, such as insulin pumps and continuous glucose monitoring (CGM) sensors, are becoming increasingly used, offering numerous short- and long-term benefits in terms of diabetes outcomes and the maintenance of patients’ balanced health state." (PMID 40564028, 2025). "However, direct evidence linking TRPML2 and TRPML3 to insulin homeostasis and diabetes remains lacking." (PMID 39996055, 2025). "However, these technological advancements have not changed diabetes management in many low- and middle-income settings, where insulin and related supplies are lacking and people with diabetes face weak health systems." (PMID 40565407, 2025). "As proper insulin uptake marks MTX response consistently in these two cohorts regardless of other comorbidities like diabetes mellitus, it is tempting to state that this easily measurable parameter can be indexed regularly to follow disease course and dynamically adjust treatment regimen." (PMID 40643485, 2025). "However, none of the included studies followed the widely recommended protocol of inducing obesity through HFD feeding before diabetes induction, a method that more accurately mimics human T2DM pathophysiology, which often involves insulin resistance secondary to obesity." (PMID 41018904, 2025). "Although short‐term intensive insulin therapy (SIIT) mitigates glucotoxicity, the effect of combining SIIT with sodium‐glucose co‐transporter 2 (SGLT2) inhibitors in hospitalised type 2 diabetes mellitus (T2DM) patients with severe hyperglycemia remains unclear." (PMID 40828947, 2025). "Additionally, kaempferol has been reported to improve insulin sensitivity and helps to regulate blood glucose, making it relevant in managing metabolic disorders, with its effects being previously reported in STZ-induced diabetes in rats." (PMID 40429855, 2025).
diabetes (continued). "Although insulin was discovered to treat diabetes, it is not used as a first-line therapy for hyperglycemia unless β cells of the pancreas are not produced enough to meet the body’s requirements, as in type 1 diabetes mellitus." (PMID 41214779, 2025). "In rats with STZ-induced diabetes, the administration of tannins (100 and 200 mg/kg of tannin fraction for 30 days) effectively reduced elevated levels of blood glucose, total cholesterol, triglycerides, and LDL cholesterol and restored insulin and HDL cholesterol." (PMID 39861406, 2025). "Variables such as diabetes duration, insulin doses, and insulin types were not consistently reported and therefore could not be analyzed." (PMID 41477679, 2025). "To ensure we include only new PD onset patients, we require that before the PD onset HbA1c, patients must have had no HbA1c above 5.7%, no diagnosis related to prediabetes or diabetes (Type 1 or Type 2), and no history of glucose-controlling medications use or insulin prescriptions." (PMID 41407881, 2025). "DM: diabetes mellitus; NGT: normal glucose tolerance; BMI: body mass index; WC: waist circumference; FPG: fasting plasma glucose; 2hPG: two-hour plasma glucose; HbA1c: hemoglobin A1c; HOMA-IR: insulin resistance by homeostasis model assessment; FI: fasting insulin." (PMID 40630340, 2025). "Metabolic regulation: Insulin signaling pathway showed nodal connections with both glucagon signaling and inflammatory pathways (IL-17 signaling, TNF signaling), proposing a unique therapeutic strategy for diabetes complications via metabolic-inflammatory crosstalk regulation." (PMID 41295287, 2025). "Sixth, insulin treatment is associated with HDF Strength(RMS) L-S, the study does not explore potential confounders, such as differences in diabetes severity or adherence to treatment regimens, that might influence this finding." (PMID 39957999, 2025). "Furthermore, the absence of dynamic blood glucose and insulin monitoring limits the conclusions to anti-inflammatory effects rather than direct therapeutic efficacy for diabetes." (PMID 41480362, 2025). "In addition, patients who managed diabetes through exercise and diet control, rather than oral medications, and those receiving only a single daily insulin injection, as opposed to multiple injections, reported better QoL." (PMID 40844966, 2025). "Type 1 diabetes mellitus is characterized by insufficient or nonexistent insulin synthesis." (PMID 40002353, 2025). "Lastly, while IF is generally considered safe, caution should be exercised in individuals with diabetes, particularly those on insulin therapy, as disturbances in blood glucose may occur if not properly monitored." (PMID 40573103, 2025). "The incidences of nulliparity, family history of diabetes, abnormal FPG, abnormal 1 h PG, abnormal 2 h PG, cesarean section (CS), and small for gestational age (SGA; birth weight < 10th percentile) were significantly higher in the insulin therapy group than in the diet therapy group." (PMID 39940296, 2025). "However, when these mechanisms are overwhelmed, β cells eventually fail, leading to type 2 diabetes mellitus (T2DM), which is characterized by chronic hyperglycemia, insulin resistance in peripheral metabolic tissues and inadequate insulin secretion from β cells." (PMID 39996055, 2025). "Additionally, participants with diabetes who failed to comply with their insulin regimen for more than four weeks without experiencing recurrent DK/DKA at any point during their illness were also assigned to the T2DM group." (PMID 41225468, 2025). "Background/Objectives: Diabetes mellitus is a growing global health concern, driving the exploration of new therapies like cannabidiol (CBD), which shows potential in improving insulin sensitivity and glycemic control, though its effects on glucose metabolism remain unclear." (PMID 40283884, 2025).
diabetes (continued). "We report a case of obese diabetes that met the diagnostic criteria for SPIDDM (probable), with GADA levels remaining extremely high for over 10 years, but without a decline in endogenous insulin secretion." (PMID 40226121, 2025). "An issue can arise, however, with genetic syndromes if diabetes is diagnosed in childhood, perhaps at a time of metabolic stress causing glucose levels to rise markedly, whence the paediatric diabetes team may conservatively assume T1DM, and start insulin with a plan for reviewing that need." (PMID 40035222, 2025). "People diabetes have complications when insulin is not given." (PMID 41190158, 2025). "While diabetes does not automatically prevent employment, safety-sensitive roles such as aviation may have restrictions for insulin-treated individuals due to their intrinsic hypoglycaemic risk." (PMID 41007688, 2025). "Overall, people with diabetic neuropathy had a mean age of 66.7 ± 7.6 years, a mean diabetes duration of 11.3 ± 6.7 years, and the mean HbA1c levels were 8.1 ± 1.5% (65 ± 7 mmol/mol); this documented a not well-compensated diabetes; in 43.8% of the cases, insulin was part of the treatment." (PMID 40564126, 2025). "Therefore, further investigation is needed to define the glycemic kinetics, efficacy, and safety of FRI insulin protocols specifically in dogs with non-ketotic, decompensated diabetes." (PMID 41150108, 2025). "Although there have been algorithms developed to assist clinicians in insulin doses, they are mostly limited to simulated settings without any human evaluations, include exclusively patients with diabetes, and none specifically target post-cardiac surgery patients." (PMID 40425725, 2025). "Furthermore, SCAAR provides information on insulin use, offering valuable insights into diabetes management; however, the absence of data on DM duration, insulin duration and type of DM represents a limitation." (PMID 40967652, 2025). "The INS variant carried by Patient 15 came from patient's father, and the four ABCC8 variants (Patients 19–22) were related to their father or mother; however, the parents did not have diabetes when their child was diagnosed." (PMID 40303944, 2025). "However, the ICI are few, and the frequency of the scattered insulin cells is reduced in T1D compared with subjects without diabetes (controls)." (PMID 38922355, 2025). "However, insulin given to COVID-19 patients with diabetes mellitus did not affect orexin A plasma concentrations." (PMID 40529720, 2025). "The limitations of the DEPS‐R in specificity and the lack of diabetes‐specific screening for people without intensified insulin therapy may contribute to the low detection rate of BED and BE in clinical care." (PMID 40440439, 2025). "In patients without diabetes mellitus, and in the absence of exogenous insulin and oral hypoglycemic agents, acute illness, and hormone deficiencies, further investigations should be requested during a supervised fast on laboratory-confirmed, symptomatic hypoglycemia." (PMID 40270996, 2025). "Unlike Akt1 and Akt3 KO mice, Akt2 KO mice develop diabetes and are insulin resistant." (PMID 40141412, 2025). "Additionally, the constitution of healthcare costs is a highly complex and interconnected systemic issue, reductions in insulin price do not be consistent to decreased expenditures for patients with diabetes or lower overall healthcare costs." (PMID 40988682, 2025). "Significant improvement in cardiovascular, antidepressant, and overall medication adherence in pharmacist-led telehealth vs nurse-led telehealth; no significant improvement in diabetes medication/insulin and adjunct antidepressant adherence vs nurse-led telehealth." (PMID 40202791, 2025). "Specifically, the dysregulation of PI3K‐Akt and Rap1 signaling may underlie both chondrocyte apoptosis in OA and impaired insulin signaling in T2DM, potentially explaining why KOA, but not HOA, was genetically linked to diabetes risk." (PMID 41476995, 2025).